SAMMSON (survival associated mitochondrial melanoma specific oncogenic non-coding RNA)
Synonyms: uc.116; LINC01212
Gene: Long non-coding RNA gene on chromosome 3 (69,999,550 to 70,518,064, forward strand). Ensembl gene ENSG00000240405.
Diseases named in the same sentence as SAMMSON in open-access papers:
SAMMSON is named in the same sentence as 21 diseases in open-access papers, as found by Europe PMC text mining. Sharing a sentence is not in itself a finding about the gene and the disease. The quoted sentences say what the papers report.
melanoma (48 papers, 2016 to 2025). A malignant, usually aggressive tumor composed of atypical, neoplastic melanocytes. "In fact, the role of SAMMSON (survival-associated mitochondrial melanoma-specific oncogenic non-coding RNA) is well documented." (PMID 39000605, 2024). "SAMMSON expression is upregulated and associated with a poor prognosis in melanoma, oral squamous cell carcinoma and liver cancers." (PMID 34827149, 2021). "SAMMSON (survival-associated mitochondrial melanoma-specific oncogenic non-coding RNA)—located downstream of the specific oncogene of melanoma microphthalmia-associated transcription factor (MITF)—is an oncogenic lncRNA expressed in more than 90% of human melanomas." (PMID 33503876, 2021). "Knockdown of SAMMSON was shown to sensitize melanoma to MAPK-targeting therapeutics as well, but its underlying mechanism is unknown." (PMID 33203119, 2020). "SAMMSON silencing causes mitochondria structure aberration and decreases the activity of respiratory complexes I and IV, leading to mitochondrial membrane potential depolarization, mitochondrial precursor-over-accumulation stress (mPOS) and cell apoptosis in melanoma." (PMID 32174794, 2020). "On the other hand, TINCR acts upstream of MITF to repress its expression and block the spread of melanoma whilst SAMMSON is frequently co-amplified with MITF in melanoma and is essential for melanoma cell proliferation and survival." (PMID 41336739, 2025). "Fifty nontargeting sgRNAs were incorporated as negative controls as well as positive controls against five known melanoma-associated lncRNAs (BANCR, CDKN2B-AS1, HOTAIR, MALAT1, and SAMMSON)." (PMID 40552742, 2025). "In melanoma, the overexpression of SAMMSON into the nucleus disrupted the CARF–XRN2 interaction, allowing CARF to enter the cytoplasm to form a complex with p32." (PMID 39408810, 2024). "In melanoma, a few lncRNAs have been identified such as SAMMSON, RMEL3, and LLME23, which are expressed in more than 90% of melanoma subtypes." (PMID 37509693, 2023). "While MITF is a melanoma-specific factor, SAMMSON has also been observed to be up-regulated in thyroid cancer and glioblastoma." (PMID 37445678, 2023). "Several oncogenes such as melanocyte inducing transcription factor (MITF) and SAMMSON exist in this amplicon that has a pivotal function in melanoma genesis." (PMID 37772815, 2023). "For instance, SAMMSON is co-induced with the melanoma-specific oncogene MITF, and it is highly expressed in most melanomas, while knock-down of SAMMSON decreases melanoma cell viability and sensitizes melanoma to therapeutics." (PMID 36869839, 2023). "SOX10 is a melanoblast/melanoma‐specific transcription factor with a binding site upstream of SAMMSON, and its silencing decreases SAMMSON expression." (PMID 37772815, 2023). "Several studies have shown that SAMMSON expression is increased in tissue and cancerous cells of melanoma." (PMID 37772815, 2023). "Ninety percent of melanoma patients express lncRNA SAMMSON, which is undetectable in normal melanocytes." (PMID 36497341, 2022). "The SAMMSON gene is co-amplified in melanomas together with MITF within the genomic locus 3p13-3p14 and is associated with poor prognosis in melanoma patients." (PMID 35159386, 2022). "SAMMSON fosters melanoma proliferation and survival by bursting mitochondrial activity and biogenesis through the p32 pathway." (PMID 36497341, 2022). "In the present study, we found that SAMMSON is expressed in more than 80% of uveal melanoma tumors at levels that are substantially higher compared to non-melanoma tumors." (PMID 34508176, 2022). "Knockdown of SAMMSON in melanoma cells impairs mitochondrial targeting of p32, leading to mitochondrial translation defects and subsequently triggering apoptotic cell death." (PMID 34414182, 2021).
melanoma (continued). "Knockdown of SAMMSON in melanoma cells decreases mitochondrial p32 levels and induces mitochondrial protein synthesis defects." (PMID 34414182, 2021). "SAMMSON expression was comparable in proliferative and invasive melanoma phenotypes, whereas MITF-M protein level was high in the proliferative and low in the invasive cultures, respectively." (PMID 34638331, 2021). "Interaction of p32 with SAMMSON oncogene (long non-coding RNA) promotes pro-oncogenic function of melanoma cells." (PMID 34711805, 2021). "SAMMSON gene is located ~30 kb downstream of MITF and both genes are co-amplified in about 10% of melanomas, and amplification of both genes is associated with poor prognosis." (PMID 34638331, 2021). "Intriguingly, increased SOX9 expression by PITX1 eventually leads to suppressive effects on cell proliferation and induction of apoptosis via downregulation of SOX10 and SAMMSON, which play an oncogenic role in melanoma." (PMID 34526609, 2021). "Previous studies have shown the involvement of exogenous p32 protein in migration and invasion of B16F10 melanoma cells and interaction of p32 with SAMMSON oncogene promoting pro-oncogenic function." (PMID 34711805, 2021). "A relationship between SAMMSON and the mitochondrial metabolism has already been described in melanoma cells." (PMID 34827149, 2021). "As a transcriptional target of SOX10, the expression of SAMMSON is detectable in more than 90% of melanomas." (PMID 34924562, 2021). "We and others demonstrated in melanoma that ASO strategy is feasible in vivo by targeting SAMMSON mRNA and the lncRNA TYRP1." (PMID 33724679, 2021). "SAMMSON was expressed in most malignant melanomas but was barely detectable in normal melanocytes and benign lesions." (PMID 34526609, 2021). "In melanoma cells, SAMMSON allows XRN2 shuttle into the nucleolus and promotes the pre-rRNA maturation." (PMID 33419375, 2020). "In melanoma patients, the SAMMSON locus is recurrently co-gained with the MITF oncogene through 3p13-3p14 focal amplification." (PMID 33329688, 2020). "SAMMSON, long non-coding RNA, was shown to be expressed in more than 90% of melanomas and co-amplified with MITF in 10% of melanomas, because of downstream coding position." (PMID 33091721, 2020). "In melanoma patients, SAMMSON is recurrently cogained with the MITF oncogene during focal amplification of chromosome 3p13-3p14." (PMID 33182489, 2020). "Meanwhile, the encoding gene of survival associated mitochondrial melanoma-specific oncogenic lncRNA (SAMMSON) also harbours the melanoma-specific oncogene MITF and it was demonstrated that SAMMSON is frequently co-amplified with it." (PMID 33203119, 2020). "SAMMSON is predominantly expressed in aggressive melanomas, where it was described as a promoter of cell growth." (PMID 32180794, 2020). "SAMMSON promotes melanoma cell viability and desensitizes the cells to MAPK-targeting cancer therapeutics." (PMID 33329688, 2020). "SAMMSON is a lncRNA that is predominantly expressed in aggressive melanomas, where it is required to stimulate the mitochondrial function of actively proliferating tumor cells." (PMID 30917553, 2019). "SAMMSON is expressed in 90% of human melanomas and is essential to the viability of melanomas, irrespective of BRAF or NRAS mutational status." (PMID 31416288, 2019). "Knockdown of SAMMSON impairs the p32 targeting to the mitochondria, whose activity is essential for quickly dividing melanoma cells and results in a mitochondrial protein synthesis defect." (PMID 30917553, 2019). "We investigated the role of SAMMSON in melanoma and found that SAMMSON was up-regulated in HCC and had prognostic values." (PMID 31164410, 2019). "LncRNA SAMMSON has recently been characterized as an oncogenic lncRNA in melanoma We performed preliminary microarray analysis and found that SAMMSON was up-regulated in HCC and inversely correlated with miR-9-3p, which plays tumor suppressive role in HCC." (PMID 31164410, 2019).
melanoma (continued). "About 10% of melanomas exhibited focal amplifications of lncRNA SAMMSON, which regulated vital mitochondrial functions and increased the clonogenic potential of melanoma cells." (PMID 30216655, 2018). "SAMMSON functions as an oncogene in melanoma and silencing SAMMSON delivers effective antimelanoma therapeutic responses." (PMID 28935763, 2017). "Several studies have identified known lncRNAs that are abnormally expressed in melanoma, such as SAMMSON, HOTAIR, SLNCR1, BANCR, SPRY4-IT1, ANRIL, Llme23, UCA1, MALATA1, GAS5, H19, CASC15, PTENP1, and MIR31HG." (PMID 28225791, 2017). "Expression of SAMMSON was detectable in over 90% of human primary melanoma and metastasis, whereas SAMMSON was undetectable in normal healthy tissue." (PMID 28350340, 2017). "In melanoma, SAMMSON is the target of the melanoblast/melanoma-specific transcription factor SOX10 and its co-factor." (PMID 28350340, 2017). "In addition to melanoma, SAMMSON expression is upregulated in several other cancers, such as hepatocellular carcinoma, breast cancer, and glioblastoma, and also influences cancer development." (PMID 39408810, 2024). "Overall, the ERV LTR-derived lncRNAs BANCR and SAMMSON, which are specifically expressed in cancer cells, are biomarkers for melanoma and could be potential targets for cancer therapy." (PMID 39408810, 2024). "SAMMSON is also a well-studied lncRNA initially described as up-regulated in malignant melanoma." (PMID 37445678, 2023). "Conversely, ectopic expression of SAMMSON confers resistance of melanoma cells to vemurafenib." (PMID 35159386, 2022). "Thus far, 8 out of 21 GLI targets we chose to validate—KRT16, S100A9, SOX9, BIRC7, EBI3, FLG, SAMMSON and SPRY2—were already implicated in melanoma pathogenesis." (PMID 36139698, 2022). "Moreover, it has been documented that long non-coding RNA (lncRNA) SAMMSON, which co-expresses with MITF, promotes melanoma growth by upregulating mitochondrial main regulatory factor p32 and targeting SAMMSON renders melanoma cells therapeutic vulnerability." (PMID 36003368, 2022). "Notably, SAMMSON expression is required for melanoma growth in vivo and in vitro and confers resistance to MAPK inhibitors." (PMID 35159386, 2022). "Intriguingly, downregulation of SOX10 expression in tumor cells was associated with decreased SAMMSON expression, suggesting that PITX1 plays a crucial role as a regulatory factor to directly suppress melanoma growth thorough the SOX9-SOX10 and SAMMSON pathway." (PMID 34526609, 2021). "Additionally, induction of PITX1 strongly suppressed SOX10 expression and SAMMSON transcription, which act as oncogenic driver genes in melanoma, via up-regulation of SOX9." (PMID 34526609, 2021). "Importantly, melanoma cells showing resistance to BRAF inhibitors were also sensitive to SAMMSON silencing." (PMID 34526609, 2021). "Reduction of mitochondrial p32 levels or SAMMSON knockdown perturbs mitochondrial respiratory chain and collapses the mitochondrial membrane potential, which eventually leads to mitochondria-dependent apoptosis of melanoma cells." (PMID 34638331, 2021). "Interestingly, the expression of SAMMSON, which is known as a melanoma-specific long non-coding RNA that is regulated by SOX1024, coincided with a reduction in SOX10." (PMID 34526609, 2021). "For example, inhibition of SAMMSON in melanoma xenografts suppressed the tumor growth." (PMID 32180794, 2020). "Knockdown of TDG also led to altered metabolic status with reduced expression of genes involved in oxidative phosphorylation; the critical role of oxidative phosphorylation in promoting melanoma growth has been recently highlighted by elucidation of the role of SAMMSON." (PMID 30674989, 2019). "In addition, SAMMSON can modulate epigenetic processes by regulating histones or DNA methylation, which is significantly upregulated in cancer; it also induces melanoma cells to develop drug resistance to BRAF inhibition by increasing oxidative phosphorylation." (PMID 39659781, 2024).
melanoma (continued). "Additionally, SAMMSON expression in melanoma cells is promoted by the SOX10 transcription factor." (PMID 33329688, 2020). "Interestingly, both MITF and the lncRNA SAMMSON reside within this amplicon, suggesting that a proportion of melanoma patients alter oxidative metabolism through two unique independent mechanisms, the SAMMSON-p32 axis and the MITF-PGC1α axis, both of which are regulated by SOX10." (PMID 31416288, 2019). "Other studies identified the role of HOTAIR, MALAT1, BANCR, ANRIL, SPRY‐IT1, SAMMSON, UCA1, and SLNCR1 in melanoma patients and cell lines." (PMID 39764216, 2024). "The SAMMSON is located 30 kilobase pairs downstream of MITF, a melanoma-specific transcriptional regulator, whose expression correlates with MITF." (PMID 37445678, 2023). "PITX1 binds to the promoter region of SOX9, promoting its transcription and thus suppressing the growth and proliferation of melanoma by inhibiting SOX10 and SAMMSON." (PMID 37841446, 2023). "SAMMSON expression is regulated by SOX10, a transcription factor located upstream of the SAMMSON transcription start site (TSS), and is involved in melanoma malignancy by enhancing mitochondrial metabolism." (PMID 33503876, 2021). "Although the SOX10-regulated lncRNA SAMMSON is co-amplified with MITF in melanoma, our understanding of how MITF-SOX10 drive melanocyte and melanoma biology, and how much of their activity is mediated by lncRNAs is largely unexplored." (PMID 31881017, 2019). "All but one (GAS5) of 13 lncRNAs reviewed are upregulated in melanoma compared with normal tissue, and three lncRNAs are suggested to be melanoma specific (RMEL3, SAMMSON, LLME23)." (PMID 28415644, 2017). "SAMMSON represents one of the most distinctive examples of a non-coding regulator that orchestrates mitochondrial function in melanoma." (PMID 41463281, 2025). "Knockdown experiments revealed that suppression of PITX1 resulted in decreased SOX9 expression, whereas overexpression of PITX1 led to activated and increased SOX9 expression, inhibiting the growth and proliferation of melanoma by suppressing SOX10 and SAMMSON." (PMID 37841446, 2023). "More recently, SAMMSON has been shown to be important for human melanoma cell growth and survival while also highlighting the role of a SAMMSON in modulating the adaptive resistance of mutant BRAF melanoma to RAF inhibitors." (PMID 36139698, 2022). "Of note, MITF, with which SAMMSON is co-amplified at 3p13-3p14, is a transcriptional regulator of lncRNA DIRC3, which is disrupted by balanced translocations in renal carcinoma and suppressed by SOX10 in melanoma cells (see Translocations)." (PMID 33329688, 2020). "Furthermore, SAMMSON knockdown decreased OXPHOS activity and mitochondrial membrane potential and impaired melanoma cell viability." (PMID 33182489, 2020). "At the initial stage of drug treatment, SOX10 may provide rapid protection on melanoma cells by upregulating pro-survival factors such as FOXD3, MITF, and SAMMSON and therefore is important for the survival of melanoma cells." (PMID 29295999, 2018). "Importantly, both SAMMSON and its role in p32 transport are likely specific to melanoma cells, since in a variety of other models p32 does not seem to require special factors for efficient import into the mitochondria." (PMID 30917553, 2019). "Six targets—S100A9, FLG, SAMMSON, LY6D, CACNA2D2, and HES1—were found to have variable expression in different melanoma cell lines, so they could not be validated as GLI targets in melanoma." (PMID 36139698, 2022).
glioblastoma (3 papers, 2020 to 2023). The most malignant astrocytic tumor (WHO grade IV). "Expression of SAMMSON has been increased in the plasma of patients with glioblastoma but not in those with diffuse neurosarcoidosis, a disorder that shares MRI signs with glioblastoma." (PMID 33634032, 2020). "SAMMSON knock-down was also observed to inactivate the PI3K/AKT pathway, suppressing the malignancy of glioblastomas." (PMID 36869839, 2023).
uveal melanoma (3 papers, 2022 to 2025). A melanoma derived from melanocytes of the uveal tract. "In uveal melanoma, SAMMSON inhibition leads to the impairment of protein translation and mitochondrial function." (PMID 36869839, 2023). "In contrast to skin melanoma tumors, where SAMMSON is invariably co-amplified with Melanocyte Inducing Transcription Factor (MITF) on chromosome 3, uveal melanoma cells are characterized by frequent (50−60%) loss of an entire copy of chromosome 3." (PMID 34508176, 2022). "Additional studies in uveal melanoma xenograft models that metastasize should further assess the impact of SAMMSON knockdown on metastatic disease." (PMID 34508176, 2022). "The present study demonstrates that SAMMSON expression is essential for uveal melanoma cell survival." (PMID 34508176, 2022). "Together with validated p32 and XRN2 interactions, these results suggest a role for SAMMSON in regulating translation and mitochondrial function in uveal melanoma." (PMID 34508176, 2022). "While 50% of uveal melanoma tumors are characterized by loss of an entire copy of chromosome 3, SAMMSON expression levels are not reduced in monosomy 3 tumors whereas the majority of genes on chromosome 3 do show a clear gene-dosage effect." (PMID 34508176, 2022). "Immunoprecipitation of both p32 and XRN2 in 92.1 and OMM1 cells revealed a 2- and 6-fold enrichment in OMM1 and a 4- and 64-fold enrichment in 92.1 of SAMMSON RNA, respectively, indicating that SAMMSON binding to these factors is conserved in uveal melanoma cells." (PMID 34508176, 2022). "Consequently, inhibition of SAMMSON impaired global, mitochondrial and cytosolic protein translation levels and mitochondrial function in uveal melanoma cells." (PMID 34508176, 2022).
breast carcinoma (2 papers, 2021 to 2023). "To explore this point, we evaluated the link between SAMMSON expression, metabolic orientation and chemoresistance in a cellular model of breast cancer, which is the foremost cause of cancer mortality in women worldwide, with recurrent incidences occurring in more than 20% of patients." (PMID 34827149, 2021). "In the present study, we analyzed the role of SAMMSON in metabolism and chemoresistance in the doxorubicin-resistant breast cancer MCF-7dox cell line." (PMID 34827149, 2021). "Thus, targeting SAMMSON expression levels represents a promising therapeutic route to circumvent doxorubicin resistance in breast cancers." (PMID 34827149, 2021). "In our model of breast cancer cells resistant to doxorubicin, the expression of SAMMSON could be part of the cellular stress response favoring ROS production and metabolic switching." (PMID 34827149, 2021).
hepatocellular carcinoma (2 papers, 2019 to 2023). A malignant tumor that arises from hepatocytes. "In hepatocellular carcinoma, SAMMSON was upregulated and promotes invasion and migration; therefore, it has an oncogenic role." (PMID 37772815, 2023). "In the present study, we investigated the role of lncRNA SAMMSON in hepatocellular carcinoma (HCC)." (PMID 31164410, 2019).